CD8A (CD8 subunit alpha)
Diseases named in the same sentence as CD8A in open-access papers (continued):
Sharing a sentence is not in itself a finding about the gene and the disease.
infection (continued). "The absolute numbers of this γδ T cell subset in blood showed no infection-related changes, whereas the percentages of CD8α+CD27+ γδ T cells within CD2+ γδ T cells in lymph nodes was slightly enhanced in infection groups." (PMID 28559930, 2017). "CD4+ and CD8α+ T cells together with B cells in different organs and blood were investigated by flow cytometry (FCM) for the first time to obtain insights into the local and systemic cellular immune response after vaccination and/or infection." (PMID 28662952, 2017). "Expression of Cd3d, Cd8a, Ifn, Ccl5 and Tbx21 remained highly upregulated 56 days post-infection whereas Ccr7 did not." (PMID 29040326, 2017). "Substitution of the CD8α TM domain decreased infection of CAR CD8 T cells regardless of the promoter used at the 1:25 and 1:50 E:T ratios." (PMID 29023549, 2017). "Furthermore, most of the immune-related genes, particularly TLR7, TRAF3, Mx, TRIM25, CD4, and CD8α, increased in response to GPV and H9N2 infection." (PMID 27916934, 2016). "Infection led to CD3+CD4+ and CD3+CD8α+ lymphocyte infiltration into the magnum of the oviduct." (PMID 27846843, 2016). "We demonstrate that serum MIF increased rapidly during the acute infection with T. gondii and promoted maturation of CD11b+ but not CD8α+ DCs." (PMID 27057101, 2016). "Of particular interest, IL-10 transcripts were strongly induced only in neonatal preCD8α Clec9A+ DCs after Lm actA-/- infection whereas adult preCD8α Clec9A+ DC and adult CD8α + DCs did not." (PMID 27074026, 2016). "In Atlantic salmon examined 17 days post-challenge with ISAV, Hetlandet al. reported the presence of CD8α-positive cells in the gill and a reduction of CD8α and MHC II labelled cells after ISAV infection using antibodies against recombinant proteins from MHC I, II and CD8." (PMID 26426066, 2015). "CD8α+ pDCs, on the other hand, respond slower but maintain a long‐lasting anti‐viral response, even 5 days after infection, possibly because they do not enter an exhaustion‐like state or constantly are replaced by new incoming pDC from other tissues." (PMID 24586061, 2014). "Analysis of γδ T cell subpopulations in the MLN revealed no significant change in the proportion of CD2+CD8α— γδ T cells in any infection." (PMID 25186625, 2014). "ANDV infection resulted in a higher expression of CD4 and TCR-β RNAs, and comparable expression of CD8α, suggesting that a robust CD4+ T cell response may contribute to viral clearance." (PMID 23383148, 2013). "Further, the depletion of MMCs prior to infection did not significantly increase the bacterial burden of CD8α+ DCs in mice infected with L. monocytogenes or L. monocytogenes L.p.FlaA." (PMID 24349458, 2013). "Following Lm-OVA infection, aged mice failed to accumulate CD8α+ DC in the spleen, and these cells expressed much lower levels of critical costimulatory molecules in the first three days following infection." (PMID 22862959, 2012). "We found that the early establishment of Lm infection within splenic CD8α+ DCs was impaired in old mice and that this population failed to accumulate in old mice later, on days 3–5 post-infection." (PMID 22862959, 2012). "In one study using the intraperitoneal infection route one of twelve cell lines was CD4- CD8α+ but this lacked expression of CD8β." (PMID 21573129, 2011). "Brain fluorescence reached medium levels of approximately 8% of serum fluorescence at later stages of the infection in CD8α−/− mice, which is more than 5-fold higher than the 1-1.5% noted in mock-infected mice." (PMID 21629771, 2011). "Even when the SG tissue was heavily infected by MCMV two and four weeks post infection, frequencies of CD11c+, MHCII+, CD8α+, DEC205+, B220−, CD4− cells among the overall SG-resident APC population remained very low (<1.5%) and total numbers remained far below their splenic counterparts." (PMID 21901102, 2011). "Upon infection with Ye CD4+ (90%) and to a lesser extent CD8α+ DCs (65%) were lost." (PMID 21124820, 2010).
infection (continued). "Upon infection with Ye, IL-12 as well as TNF production was induced in CD4+ and CD4−CD8α−, but decreased in CD8α+ DCs, which in turn may account for reduced T-cell priming by CD8α+ DCs." (PMID 21124820, 2010). "In the first set of experiments, DC were separated on the basis of CD11c, CD8α and CD45RA expression into CD8α DC, pDC (CD11c+CD45RA+CD8α− DC) and DN DC and examined for their capacity to present MHC class I and II antigens at both 48 and 72 h after infection." (PMID 18301768, 2008). "Namely, CD5, CD8A, CD6 and CD244, C-C and C-X-C motif chemokines (CXCL5 CXCL6, MCP-4, and CCL20), as well as CD40, PDL-1, CUB domain-containing protein 1 (CDCP1) and interleukin-12B (IL-12B) were elevated in the late infection group compared to the unexposed group." (PMID 41510260, 2025). "Similarly, lack of protection against heterologous challenge infections induced by a live attenuated vaccine (LAV) candidate correlated with an absent response of CD8α+ lymphocytes." (PMID 35215216, 2022). "We found that the MDV RB1B strain transiently induced higher percentage of γδ T cells in the lung at 7 dpi but not in the spleen at any time-point and no significant expansion of CD8α+ T cells in spleen and lung over the course of infection, compared to mock-infected birds." (PMID 33659011, 2021). "However, Batf3−/− mice began to clear infection by day 5, before the reappearance of CD8α+ cDCs, suggesting that clearance was not due to the reappearance of CD8α+ cDCs, but rather due to some other mechanism." (PMID 32669460, 2020). "This leads to enhanced differentiation of naïve T-helper cells into effector T-helper/Memory cells [CD3+CD4+CD8α+CD8β-CD27-], which are capable of secreting high amounts of effector cytokines leading to efficient clearance of heterologous challenge virus at the site of infection." (PMID 33391267, 2020). "This process involves the CD8α+ DCs, which through TLR9-dependent recognition of the mtDNA (released from dead neutrophils) release IL-12p70, which generates FoxP3+Tregs from conventional CD4+T cells during a high dose infection, whereas a low dose infection induces CD8+T cell generation." (PMID 33643304, 2020). "CD8+ and CD4+ T cells of the immunized mice were depleted by intraperitoneal injection (4 times) of anti-CD8α and anti-CD4, respectively, at the indicated time points around the infection time point and the effects of such depletion were confirmed after 4 days of the last injection." (PMID 29370185, 2018). "Two weeks after infection, however, OT-I proliferation was diminished in DT-treated mice, and by 3 weeks after infection, OT-I proliferation occurred regardless of whether langerin+ CD8α+ DCs had been depleted (data not shown)." (PMID 29867941, 2018). "Ag-driven changes in expression of CD8α and CD11a have been used as “surrogate activation markers” approach to track pathogen-specific CD8 T cell responses to infection in outbred mice without a priori knowledge of MHC class I restriction and/or specific epitopes." (PMID 30515169, 2018). "Infection elicited an increase in specific IgA, IgG, and IgM antibodies and relative quantitative changes in several leukocyte populations, including CD3, CD4, CD8α, CD8β, MHC II, KuL01, and γδ TCR positive cells, both in the gastrointestinal tract and systemically." (PMID 26664914, 2014). "Our results may also indicate that the role MMCs play in T cell activation is independent of the antigen level of CD8α+ DCs in infections with wt L. monocytogenes." (PMID 24349458, 2013). "Moreover, lack of accumulation of splenic CD8α+ DCs later in the infection correlated to reduced capacity of transferred adult CD8 T cells to accumulate in old recipients." (PMID 22862959, 2012). "However, on days 3 and 5 following infection, there was a marked increase in the critical CD8α+ DC subset in adult animals that was notably absent in the old mice." (PMID 22862959, 2012).
infection (continued). "However, CD8A+ cells also ubiquitously showed highest levels of CCL5 (RANTES), a chemokine previously shown to maintain CD4+ TRM cells after infection or sensitization, but that also attracts monocytes which were shown to promote the survival of MF cells in a mouse model." (PMID 33968070, 2021). "We determined if DCs from these mice behave differently following infection with LAT(+) versus LAT(−) viruses, and whether the phenotype of CD8α−/− mice could be restored to that of WT mice by adoptive transfers of WT CD8+ T cells or bone marrow (BM) derived CD8α DCs." (PMID 24695322, 2014). "In this context, non-infected XCR1+ (CD8α+) DCs were critical and responsible for the initial activation of naive CD8+ T cells by cross-priming at later time points of infection and were supported by previously primed CD4+ T cells." (PMID 32765505, 2020). "In the context of infection, OT1 T cells treated with anti-CD8β downregulated IL-7Rα similarly, but anti-CD8α treated did not." (PMID 30735510, 2019). "We unequivocally show that ISG15 production during Toxoplasma infection results in the recruitment of CD8α+ dendritic cells (DCs) to the site of infection and that ISG15 exclusively stimulates IL-1β and not IL-12 production by CD8α+ DCs." (PMID 29891555, 2018). "Strikingly, we found that the infection with HeV and NiV-B did not modify the expression levels of lymphocyte markers (CD2, CD3D, CD3E, CD3G, CD4, CD8A and CD27) in the lung tissue by 5 dpi." (PMID 29538374, 2018). "During the PE period, the slightly but not significantly higher levels of CD4+CD8α– T helper cells and γ/δ T lymphocytes in the PCV2-vac group were attributed to changes independent of infection." (PMID 24735253, 2014). "Additionally, swIAV infection also led to an increase of cells represented by cluster 10 which consisted of CD3+ T cells that were negative for CD4, CD8β and TCR-γδ, but CD2+CD8α+perforindim." (PMID 40484956, 2025). "In the absence of infection, the splenic phagocyte population (CD4− CD8a− CD19− B220− CD11b+ splenocytes) of VAD mice contained a significantly (P < 0.05) larger proportion of neutrophils (CD4− CD8a− CD19− B220− CD11b+ Ly6G+ splenocytes) compared with control mice." (PMID 38374245, 2024). "This negative impact of DON on CD8α and CD27 expression levels could lead to a partial impairment of T-cell stimulation and a suboptimal T-cell response following vaccination or infection of pigs." (PMID 31694331, 2019). "The overall number of OT-I cells, and the percentage of proliferating cells, was significantly lower in the spleen of langerin+ CD8α+ DC-depleted mice 1 week after rBCG-OVA infection, as well as at 2 weeks after infection in terms of OT-I number, compared to non-depleted mice." (PMID 29867941, 2018). "We document a sharp increase in the inflammatory response in terms of Ifng, Tnfa, Il6, Il1b, Il1r1, Cxcl9 and Cxcl10 expression already on day 6 post-infection in WT mice, and of Cd8a on day 7, which were essentially absent in ST2-/- mice on day 5 to 7 after PbA-infection." (PMID 28448579, 2017). "Interestingly, our work revealed that the depletion of langerin+ CD8α+ DCs lead to reduced CD8+ T cell activation and proliferation during the first week of BCG infection; however, 2 and 3 weeks after infection, CD8+ T cells proliferated in both depleted and non-depleted mice." (PMID 29867941, 2018). "Thus, the infection establishment bottleneck in the airways was not greatly affected by CD4 or CD8α depletion, although the few Mtb that entered the lung parenchyma were uncontrolled in the absence of CD4 T cells or CD8α+ lymphocytes and disseminated within the lung and to the LNs." (PMID 39912921, 2025).
immune dysfunction (362 papers, 2006 to 2026). "C5, which expressed CD8A and CD8B, was distinguished by elevated expression of GZMK, which has been recently described as a hallmark of immune dysfunction in inflammation." (PMID 35483355, 2022).
bacterial infection (220 papers, 2007 to 2025). "Although significant insights into the beneficial role of langerin+ CD8α+ DCs in blood-borne bacterial infection are presented in this study, the mechanism of protection was not fully elucidated in this work." (PMID 29867941, 2018). "Activation of effector or memory antigen-specific CD8 T cells by exposure to viral or bacterial infection induces down regulation of CD8α and up-regulation of CD11a." (PMID 24936199, 2014). "Similar results concerning CD8A mRNA in the spleen and thymus following viral and bacterial infection has been reported." (PMID 24505360, 2014). "Despite this heterogeneity, priming of CD8 T cells against intracellular viral and bacterial infections is mediated almost entirely by the CD8α+ dendritic cell subset." (PMID 22862959, 2012). "However, despite their localization and ability to promote both IL-12 and CD8+ T cell responses, little is known about the importance of CD8α+ DCs in mediating immune responses to systemic bacterial infections." (PMID 29867941, 2018). "Langerin+ CD8α+ DCs, resident in the marginal zone of the spleen, are localized for effective sampling of the blood; however, to the best of our knowledge, the role of these DCs in protection against systemic bacterial infection is yet to be reported." (PMID 29867941, 2018). "Of note, for CD4+ T cells which are frequently involved in immune responses to bacterial infections, for example via IL17 production, no up-regulation of the activation-associated CD8α molecule could be found." (PMID 28559930, 2017). "Flagella from Salmonella, Yersinia, and Pseudomonas activate the NLRC4 inflammasome in splenic CD8α+ DCs to release IL-1β and IL-18; IL-18 can stimulate IFN-γ production from non-cognate memory CD8+ T cells in the spleen thereby enhancing host resistance to bacterial infection." (PMID 24409181, 2013). "CD8α+ DCs were claimed to be specialized in the induction of anti-viral CD8+ T cell responses, in part because of their cross-presenting abilities, whereas CD8α− DCs were proposed to be primarily involved in CD4+ T cell immunity, particularly during bacterial infections." (PMID 22399974, 2009).
CD8A also shares sentences with these, for which no sentence is quoted: non-small cell lung carcinoma (404 papers); tuberculosis (250); co-infection (220); infectious disease (202); Immunodeficiency (193); head and neck squamous cell carcinoma (181); lymph node metastasis (160); sarcoidosis (151); Hypertension (133); Hepatitis (132); encephalitis (122); rectal cancer (116); T-cell lymphoma (112); multiple myeloma (109); adenocarcinoma (100); Chagas disease (100); ovarian tumor (93); Insulin resistance (91); leishmaniasis (89); emphysema (85); inflammation (85); liver disease (84); clear cell renal cell carcinoma (80); hematological malignancies (76); esophageal squamous cell carcinoma (75); graft versus host disease (74); Allergy (69); chronic obstructive pulmonary disease (68); lung squamous cell carcinoma (68); pulmonary fibrosis (65).
A further 1,507 diseases each share a sentence with CD8A in 62 papers or fewer.